IL1B (interleukin 1 beta)
Diseases named in the same sentence as IL1B in open-access papers (continued):
Sharing a sentence is not in itself a finding about the gene and the disease.
osteoarthritis (continued). "Moreover, the inhibition of the NF-κB signaling pathway by IL-1β and TNF-α decreases the inflammation of joints and tissue degradation and prevents the effects of iNOS and MMP, which cause inflammation and articular cartilage breakdown in osteoarthritis." (PMID 39204123, 2024). "In patients with osteoarthritis, these cytokines could also result in the impairment of tissues in the musculoskeletal system, wherein IL-1b could play a critical role in cartilage damage and TNF-alpha was associated with triggering further inflammatory reactions." (PMID 38173729, 2023). "Pro-inflammatory cytokines such as TNFα, IL-1β, and IL-6 accelerate the aging process of mesenchymal stem cells, impairing their ability to differentiate into other cells and subsequently alter osteochondral homeostasis in the elderly population, leading to osteoarthritis." (PMID 38201942, 2023). "Therefore, considering the crucial role of inflammation in both OA and ferroptosis, this study was designed to examine the effects of ferroptosis and its inhibitors on IL-1β-stimulated osteoarthritis, aiming to provide some valuable clues for future explorations." (PMID 36950524, 2023). "Therefore, we screened three types of genes: genes that were down-regulated when hUC-MSCs-Exos were added to IL-1β-induced osteoarthritis cartilage models; genes that were up-regulated when IL-1β was added to normal chondrocytes; genes related to osteoarthritis in the GeneCards database." (PMID 37724890, 2023). "Thus, inhibiting IL-1β secretion and IL-1β-induced degradation of the cartilage matrix may provide an effective therapeutic target for the prevention and treatment of osteoarthritis." (PMID 37953787, 2023). "In addition, with the discovery of the relationship between osteoarthritis and IL‐1β‐induced chondrocyte apoptosis, there is increasing evidence that IL‐1β can induce apoptosis, such as cardiomyocyte, nucleus pulposus cells, human umbilical vein endothelial cells, β‐cells, and fibrosus cells." (PMID 36705417, 2023). "Moreover, GSK-J4 suppressed the IL-1β-mediated increase in the expression of the cartilage-degrading matrix metalloproteinases 9 (MMP9) and 13 (MMP13) and ADAMTS5 in HACs and, therefore, has the potential to attenuate cartilage loss in osteoarthritis patients." (PMID 35915507, 2022). "Inflammation: The critical cellular component of articular cartilage, namely chondrocytes, contributes to the pathogenesis of osteoarthritis (OA) in which IL-1β is a critical contributor to OA development; antagonizing IL-1β activities may be of benefit to these patients." (PMID 36355554, 2022). "Previous studies used rat chondrocytes pretreated with Achyranthes bidentate Blume at 3-μg/mL, 10-μg/mL, and 30-μg/mL, and subsequently stimulated with IL-1β (10-ng/mL) and discovered that Achyranthes bidentate Blume might be a potential drug for treating osteoarthritis." (PMID 35001833, 2022). "Nobiletin suppressed IL-1β-induced proinflammatory mediators, including prostaglandin E2, nitric oxide, cyclooxygenase-2, inducible nitric oxide synthase, tumor necrosis factor-a, and IL-6 by inhibiting Akt and NF-κB activation in human osteoarthritis chondrocytes." (PMID 34066937, 2021). "The RT-PCR data manifested that the expression of M1 macrophage markers (TNF-α, IL-1β, and iNOS) were significantly upregulated, while the expression of M2 macrophage markers (IL-10 and Arg-1) was significantly downregulated in synovial tissues of osteoarthritis patients." (PMID 34652255, 2021). "Therefore, we analyzed whether FA could suppress oxidative stress in osteoarthritis chondrocytes stimulated by IL‐1β." (PMID 34078001, 2021). "In the osteoarthritic milieu, mechanical stress or pro-inflammatory cytokines, like TNF and IL1B, leads to NF-κB-pathway activation, which causes the expression of catabolic factors like NO, MMPs and ADAMTS proteases inducing cartilage breakdown and progression of osteoarthritis." (PMID 34440921, 2021).
osteoarthritis (continued). "Interleukin-1β (IL-1β), as one of the most common proinflammatory cytokines, suppresses the synthesis of proteoglycan and collagen and increases significantly in chondrocytes and synoviocytes of osteoarthritis patients, suggesting that IL-1β plays a crucial role in osteoarthritis development." (PMID 34164391, 2021). "Besides, an early study in osteoarthritis also suggested that IL-1β could hence NF-κB/HIF-2α activation through the PI3K/AKT pathway." (PMID 32123166, 2020). "Therefore, this unique disease-specific and inflammatory-protective feature may explain lower reactivity of osteoarthritis adipose tissues to IL-1β and consequently lower-grade inflammation, comparing with RA." (PMID 30280295, 2019). "As demonstrated in chondrocytes isolated from osteoarthritis patients, pretreatment with isofraxidin prior to IL-1β could inhibit IL-1β-stimulated expression of iNOS and COX-2 that in turn blocked the production of nitric oxide (NO) and prostaglandin E2 (PGE2)." (PMID 31388349, 2019). "This study showed that SAMC may play a protective role in IL-1β induced osteoarthritis (OA) model." (PMID 29333456, 2017). "To explore whether osteoarthritis contributes to the development of neuroinflammation and possibly AD pathology, we employed somatic mosaic expression of IL-1β in the knees and temporomandibular joints of the Col-IL1βXAT transgenic mouse model of osteoarthritis." (PMID 21899735, 2011). "Given the role of IL-1β in diseases such as type 2 diabetes, gout and osteoarthritis, which all involve NLRP3, a small molecule such as CRID3 could have promise therapeutically and be an alternative to IL-1β biologics such as the anti-IL-1β antibody Canakinumab and the IL-1 Trap Rilonacept." (PMID 22216309, 2011). "In addition to anabolism of chondrogenesis by simvastatin, there is evidence that statins can elicit anti-inflammatory actions in activated human chondrocytes, IL-1β-stimulated human chondrocytes, and experimental osteoarthritis in rabbits by inhibiting the level of matrix metalloproteinase (MMP)." (PMID 19912653, 2009). "Increased levels of IL-1β, IL-6, TNF-α, and PGE2 were reported in synovial fluid samples from patients with TMD, particularly in cases with degenerative joint disease and internal derangement." (PMID 40649748, 2025). "The reduced expression of interleukin-1β (IL-1β) upregulates the expression of MMP13 and COL10A1 genes, thereby mitigating the inflammatory response in osteoarthritis (OA)." (PMID 39857301, 2025). "Polyphyllin VII achieves the treatment of osteoarthritis by reducing TNF-α, IL-6, and IL-1β levels in knee joint fluid and inhibiting IL-1β, MMP9, and ADAMTS-5." (PMID 40520186, 2025). "Rg1 (10 μg/mL) treatment for 24 h suppressed IL-1β-induced mRNA expression of MMP-13 and COX-2 by 7.5- and 2.2-fold, respectively, in human chondrocytes from osteoarthritis patients with knee replacement." (PMID 40507179, 2025). "In this study, we also observed that in the osteoarthritis model, the levels of TNF-α, IL-1β, and IL-6 were significantly elevated." (PMID 39754163, 2025). "Specifically, IL‐1β was used to stimulate ATDC5 cells, thereby emulating the authentic state of chondrocytes in osteoarthritis." (PMID 39846237, 2025). "For example, HOTAIR may promote the death of IL-1β-induced chondrocytes by regulating the miR-222-3p/ADAM10 axis, triggering inflammatory responses, causing extracellular matrix degradation, and inducing oxidative stress during the progression of osteoarthritis." (PMID 41299664, 2025). "This aligns with previous research, where the implantation of iPSC-MSC-derived chondrocytes significantly reduced inflammatory markers, such as IL1B and TNFA, in an osteoarthritis rabbit model." (PMID 39988676, 2025). "The expression of inflammatory biomarkers MyD88, p-IκBα, NF-κB, IL-6, IL-1β, and TNF-α in synovial fluid was lower in the curcumin-treated group compared to osteoarthritis rat groups." (PMID 40507179, 2025).
osteoarthritis (continued). "HA injections have shown the ability to slow osteoarthritis progression by reducing glycosaminoglycan release and pro-inflammatory molecules, such as MMP-13, MMP-3, and IL-1β." (PMID 40943818, 2025). "CK treatment reduced IL-1β-induced iNOS, MMP-13, pJNK, pp38, and pErk expression and inhibited glycosaminoglycan release in chondrocytes from osteoarthritis patients." (PMID 40507179, 2025). "IL-1β and TNF-α have been shown to incite the progression of osteoarthritis by promoting the catabolic cascade." (PMID 38255841, 2024). "IL-1β and TNF-α expedite the advancement of osteoarthritis through the facilitation of the catabolic cascade." (PMID 38255841, 2024). "In a mouse model of posttraumatic osteoarthritis, curcumin has been found to slow the progression of osteoarthritis and relieve its symptoms by reducing the levels of MMP-1, MMP-3, MMP-13, ADAMTS5, IL-1β, and TNF-α." (PMID 37938371, 2024). "AAVs expressing CRISPR-Cas9 were used to target NGF, IL-1β, and MMP13, which are commonly upregulated in osteoarthritis." (PMID 39598601, 2024). "This study assessed the clinical efficacy of a single intra-articular stanozolol injection in canine knees with degenerative joint disease (DJD) and its correlation with serum IL-1β levels." (PMID 38731355, 2024). "The pathogenesis of osteoarthritis involves the activation of the inflammatory cascade through the stimulation of various cytokines such as TNF-α, IL-10, IL-8, and IL-1β." (PMID 38327525, 2024). "PD significantly delays the progression of osteoarthritis induced by ACLT, effectively inhibits IL-1β-induced joint inflammation, bone metabolic remodeling and extracellular matrix degradation." (PMID 39840130, 2024). "IL-1β, IL6, and TNF-α induce chondrolysis, leading to arthralgia and/or the progression of osteoarthritis." (PMID 39850191, 2024). "In vitro studies have demonstrated that DFO can inhibit the degradation of type II collagen in osteoarthritis cartilage while also reducing the expression of inflammatory factors such as MMP-1, MMP-13, IL-1β, and TNF-α." (PMID 39744014, 2024). "In another study, in osteoarthritis patients, there were significant positive correlations between ACRP-30 levels in the synovial membrane and plasma levels of IL-4, IL-1β, G-CSF, and GM-CSF." (PMID 38674217, 2024). "In another study, a higher level of IL-1β was also detected in samples from ORD patients (ankylosing spondylitis and osteoarthritis)." (PMID 39796056, 2024). "IL-1β-induced degradation of ECM was modulated by LINC00623 due to regulation of miR-101 and HRAS, leading to regulation of senescence and apoptosis of osteoarthritis chondrocytes." (PMID 37779916, 2023). "In rat cartilage tissue of osteoarthritis, miR-137 is also downregulated, and its over-expression can reduce the inflammatory factors (TNF-α, IL-1β, IL-6) via downregulating the TCF4-AMPK/NF-κB pathway." (PMID 38138985, 2023). "In this regard, Velloso Alvarez et al19 showed that ACS is a strategy to improve the clinical symptoms of horses with osteoarthritis so that 50% ACS increases IL-10 expression and decreases IL-1β in cartilage." (PMID 37645547, 2023). "Inflammation, which is mainly sustained by pro-inflammatory cytokines such as IL-1b, TNF, and IL-6, plays an important role in osteoarthritis progression." (PMID 37316888, 2023). "Tetramethylpyrazine protects chondrocytes by reducing endoplasmic reticulum stress through inhibition of IL‐1β‐induced GRP78 and CHOP expression, which is likely to be a potential therapeutic agent for osteoarthritis." (PMID 36705417, 2023). "In addition, miR-144-3p is also involved in regulating the proliferation of colorectal cancer cells, and one study found that miR-144-3p could improve osteoarthritis by targeting IL-1β, suggesting that miR-144-3p may have potential therapeutic implications for osteoarthritis." (PMID 37340458, 2023). "IL‐1β‐induced chondrocyte injury model and monosodium iodoacetate (MIA)‐induced rat osteoarthritis model were used." (PMID 37249294, 2023).
osteoarthritis (continued). "High levels of representative pro-inflammatory cytokines, IL-1β and TNF-α, have been observed in the synovium of patients with osteoarthritis." (PMID 37175932, 2023). "For instance, 10 mg/kg per day of shikonin was found to suppress inflammation by modulating PI3K/Akt signaling pathway in a rat model of osteoarthritis by inhibiting TNF-α, IL-1β, and inducible nitric oxide synthase (iNOS) levels." (PMID 37763983, 2023). "Specifically, inflammatory cartilage tissue releases cytokines such as interleukin (IL)-1β, IL-6, and tumor necrosis factor-α (TNF-α), which are responsible for cartilage matrix degradation and bone destruction in osteoarthritis." (PMID 37718444, 2023). "Knockdown of DUSP5 can inhibit IL-1β-induced expression of inflammatory genes and activation of NF-κB and ERK signaling pathways, increasing the incidence of osteoarthritis." (PMID 37766214, 2023). "The potent pro-inflammatory cytokine interleukin-1β (IL-1β) modulates MMP13 expression and is therefore a critical cytokine during osteoarthritis progression." (PMID 36672165, 2023). "In Module 2, the PI3k-Akt signaling pathway is closely involved in the inflammatory response to induce MMPs, Adamts, IL-1β, and TNF-α in osteoarthritis." (PMID 35563641, 2022). "The inhibitory effect of Mg2+ on IL-1β, MMP13, and ADAMTS5 indicates that it has a certain potential in the treatment of osteoarthritis and 5–7.5 mM Mg2+ was most effective in inhibiting cartilage catabolism." (PMID 36546928, 2022). "While FRZB, important in the progression of osteoarthritis, was decreased (FC = 0.26), mainly the inflammatory factors related to osteoarthritis such as IL1R (FC = 1.24), IL-1b (FC = 2.31), MMP9 and PTGS2 showed an increased expression after the intervention." (PMID 35159340, 2022). "Local synovial proinflammatory cytokines IL-1β, TNF-α, and IL-6A are detectable in early osteoarthritis and are related to the disease progression and joint pain of OA." (PMID 35656456, 2022). "Disease conditions, such as local and systemic infections, septic shock, degenerative arthritis and other autoimmune diseases appear to be regulated by TNF-α and IL-1β." (PMID 36678378, 2022). "Among them, interleukin 1 beta (IL-1β) and tumor necrosis factor-alpha (TNF-α) are the main factors that accelerate degenerative arthritis by inducing the expression of other cartilage ECM-degrading factors (iNOS, PGE2, MMPs, and ADAMTS-4)." (PMID 35326137, 2022). "MALAT1 is upregulated in osteoarthritis and facilitates cartilage ECM degradation in IL-1β-induced chondrocytes." (PMID 35626352, 2022). "The aim of the study was to set-up an in vitro model of osteoarthritis and aging, focusing on the sex differences by culturing male and female fibroblast-like synoviocytes (FLSs) with IL1β, hydrogen peroxide (H2O2), IL1β+H2O2 or a growth medium (control)." (PMID 36498698, 2022). "SHH autocrine treatment of osteoarthritis MSC stimulates proliferation, chondrogenesis, hypertrophy, and replicative senescence with elevated SASP gene expression including IL1B, IL6, CXCL1, and CXCL8." (PMID 34646822, 2021). "In particular, IL-1β and TNF-α can stimulate IL-6 expression, and IL-6 is a biomarker reflecting the severity of osteoarthritis." (PMID 34574569, 2021). "Cartilage tissues, from healthy subjects and patients with osteoarthritis, were collected for histology and expression of Core binding factor-β, MMP-13, IL-1β, COMP, and YKL-40." (PMID 33573620, 2021). "Several cytokines (such as IL-1β, lL-6, IL-8, IL-10, and TNF-α) and MMPs have been reported to be elevated in the joint space of patients with osteoarthritis." (PMID 34034772, 2021). "Such as has_circ_0136474, which regulates IL-1β-Induced chondrocyte injury through miR-766-3p/DNMT3A Signaling Pathway; Circ-BRWD1, which contributes to osteoarthritis development through the modulation of miR-1277/TRAF6 axis." (PMID 34652255, 2021).
osteoarthritis (continued). "Studies have proven that many pathological changes in osteoarthritis result from chronic low-grade inflammation mediated by inflammatory cytokines such as TNF-α and IL-1β." (PMID 34210342, 2021). "Finally, as FA significantly enhanced the Sirt1/AMPK/PGC‐1α signaling pathway, we investigated whether suppression of SIRT1 activity by Sirtinol, a SIRT1 inhibitor, could abolish the protective effects of FA on IL‐1β‐induced degeneration of osteoarthritis chondrocytes." (PMID 34078001, 2021). "Inflammation plays an important role in the pathogenesis of OA, in which the chondrocytes, synovial membrane, and surrounding tissues produce large amounts of inflammatory factors such as IL-1β, IL-6, TNF-α, that accelerate the progression of osteoarthritis." (PMID 34976968, 2021). "In the rat osteoarthritis model, GAS also has a protective role in chondrocyte apoptosis stimulated via IL-1β." (PMID 33505583, 2021). "In mice with osteoarthritis (OA), EMF inhibited the expression of inflammatory cytokines, including IL‐1β, ADAMTS4, and MMP13." (PMID 34774092, 2021). "After ATDC5 cells were induced by IL-1β, the expression of SREBF2 in osteoarthritis cells was detected by RT-qPCR." (PMID 34806937, 2021). "The predictive strength comprising TRD2 + IL-6 + IL1β + GGGGCT + AGC provedto be the best (AUC: 0.91, 95%CI: 0.87–0.95) for discriminating osteoarthritis patients from controls." (PMID 34073132, 2021). "In one study, RvD1 was found to inhibit the IL-1β-mediated upregulation of COX-2, PGE2, MMP13, and nitric oxide and to prevent chemically induced apoptosis in human osteoarthritis chondrocytes." (PMID 33540695, 2021). "According to a previous study, REM can repair post-traumatic osteoarthritis cartilage damage by inhibiting PI3K/Akt/NF-κB phosphorylation, reducing cartilage matrix degradation and inhibiting IL-1β-induced apoptosis of articular chondrocytes." (PMID 34612779, 2021). "Core binding factor-β was highly expressed in the osteoarthritis cartilage (p < 0.001), and MMP-13, IL-1β, COMP and YKL-40 expression were greater than found in normal cartilage (p < 0.001)." (PMID 33573620, 2021). "It is reported that YAP expression is up-regulated in human and mouse osteoarthritis cartilage and chondrocytes, and silencing of YAP can inhibit IL-1β induced chondrocyte apoptosis." (PMID 34454425, 2021). "Circ‐IQGAP1 promotes IL‐1β‐induced chondrocyte apoptosis, inflammation, and extracellular matrix degradation by miR‐671‐5p/TCF4 axis in osteoarthritis." (PMID 33675175, 2021). "Expression of USP5 was found upregulated in RA-FLS compared with that in osteoarthritis- (OA-) FLS, and IL-1β stimulation increased USP5 expression in a time-dependent manner." (PMID 32214906, 2020). "Peimine inhibits IL-1β-induced inflammation in mouse chondrocytes through suppressing the MAPK pathway activation, and plays pharmacological effects in a mouse model of osteoarthritis." (PMID 32131410, 2020). "The mRNA expression of pro-inflammatory mediators IL-1β and TNF-α decreased significantly in the FJH-KO supplemented rats compared with in rats with MIA induced osteoarthritis (p < 0.05)." (PMID 33233504, 2020). "IL-1β upregulates both iNOS and COX-2 in osteoarthritis, leading to increased production of NO and PGE2, respectively." (PMID 32189997, 2020). "Proinflammatory cytokines, such as IL-1β and TNF-α, are among the mediators secreted in early osteoarthritis." (PMID 32189997, 2020). "For animal studies, agents, such as interleukin-1 beta (IL-1β) and monosodium iodoacetate (MIA), were used to induce osteoarthritis in the animal models." (PMID 32189997, 2020). "In vitro and in vivo studies demonstrated that CJM reduced the IL‐1β‐, IL‐6, IL‐17‐ and TNF‐α‐induced up‐regulation of MMP3, MMP13, ADAMTS4, ADAMTS5 and COX‐2 and blocked osteoarthritis development in a destabilization of the medial meniscus mouse model." (PMID 31148341, 2019).